IL13 (interleukin 13)
Diseases named in the same sentence as IL13 in open-access papers (continued):
Sharing a sentence is not in itself a finding about the gene and the disease.
malaria (continued). "Furthermore, some polymorphisms in the IL13 gene promoter region have been shown to be associated with protection against severe malaria in a Thailand study, and with S haematobium infections in Mali." (PMID 24098393, 2013). "In addition, IFN-γ (intracellular and plasma) and IL-13 were also associated with malaria incidence, but these were dependent on age and/or previous episodes." (PMID 22280502, 2012). "In the present study, fine association mapping for a cytokine gene cluster including IL4, IL5, and IL13 on chromosome 5q31 was conducted using the same malaria subjects to refine the region containing a primary variant or a haplotype susceptible to severe malaria." (PMID 19840389, 2009). "Several polymorphisms affecting IL-4, IL-10, IL-13 genes, lead to changes in cytokine production levels that may impact isotype switching as well as cell interaction and thus be associated with immune-related diseases such as malaria." (PMID 23668806, 2013). "The increased production of IL-13, an archetypal Th2 cytokine with pro-fibrotic properties, by children with greater exposure to malaria, and its association with hepatosplenomegaly may be due to the necessity to repair tissue damage caused by an inflammatory response." (PMID 19149774, 2009). "Given that activated basophils are primary sources of the regulatory cytokines IL-4 and IL-13, we sought to examine the contributions of these mediators to basophil-dependent phenotypes in malaria." (PMID 38780542, 2024). "IFN-γ, IL-6, and IL-13 levels were significantly increased in coinfections compared to malaria monoinfections, as reported by two studies." (PMID 36716305, 2023). "Either increased or decreased levels of IL-4, IL-12, and IL-13 were observed in malaria monoinfection compared to dengue virus monoinfection." (PMID 36716305, 2023). "The results herein provide evidence for the association of TLR4 and related genes, ICAM1, IFNGR1, IL13, and IL6, as well as ABO, with the incidence of clinical malaria." (PMID 37287037, 2023). "Nevertheless, a protective role of IL-13 in malaria pathology was observed in individuals with a single C-to-T substitution in the IL-13 promoter." (PMID 36293524, 2022). "Patients infected with P. vivax or P. falciparum presented an increase in IFN‐γ, TNF‐α, IL‐6, IL‐8, IL‐10, IL‐13, MIP1β, and G‐CSF levels during the malaria acute phase." (PMID 29314720, 2018). "In the present study, plasma levels of IL-4, IL-7, IL-12p70, and IL-13 were more elevated in subjects purely with dengue fever than in those with malaria mono-infection or malaria and dengue co-infection." (PMID 26271921, 2015). "An antigen-specific up-regulation in IL-13 was observed post-vaccination in the two CSP study subjects who were completely protected against malaria following vaccination with the antibody-inducing vaccine RTS,S/AS02A along with MVA-CS." (PMID 26256523, 2015). "IL-4 and IL-13 plasma levels were also previously found to be higher in dengue fever compared to malaria cases." (PMID 26271921, 2015). "Subjects with severe malaria had higher levels of interleukin (IL)-2 and IL-13 than subjects with hyperbilirubinaemia." (PMID 26466783, 2015). "This is also consistent with linkage analyses in mice and genetic studies in humans showing an association of IL3, IL4, IL13, IRF1, and ARHGAP26 with parasitaemia, mild malaria or severe malaria." (PMID 24884991, 2014). "IFN-γ, IL-5 and IL-13 to TT were reduced in HIV-exposed-uninfected infants; infant malaria and HIV were associated with lower IFN-γ, IL-5 and IL-13 responses to both immunogens." (PMID 21040693, 2010). "Current infant malaria and infant HIV infection were associated with broad reductions in IFN-γ, IL-5 and IL-13 responses." (PMID 21040693, 2010). "In this study rs1881457 was found to be significantly associated with severe malaria, and this SNP was included in a haplotype block encompassing the whole RAD50 gene and the promoter of IL13." (PMID 19840389, 2009).
malaria (continued). "Plasma IL-12p70, sTNF-RII, IL-10 and IL-13 levels correlated with relative exposure to malaria, and with hepatosplenomegaly." (PMID 19149774, 2009). "Importantly, three out of the four patterns for malaria had anti-inflammatory response cytokines in the clusters (IL-4, IL-13, IL-1RA)." (PMID 35811678, 2022). "Furthermore, TNF was found elevated in both groups of malaria mono-infection and co-infection with dengue whereas IL-13 was detected in higher amounts in the groups of dengue mono-infection and co-infection." (PMID 26271921, 2015). "The CT/CC genotype for the rs20541 SNP in IL13 locus (OR=1.38, 95%CI 1.11-1.76, p=0.003) and the TLR9 rs187084 SNP (additive T, OR=1.23, 95%CI 1.05-1.44, p=0.010) were associated with susceptibility to malaria following univariate analysis." (PMID 24312262, 2013). "As such, the presence of the TA haplotype could be altering the gene-gene interactions of IL-13 and IL-13Rα1, thereby promoting enhanced IL-4 production leading to inhibition of erythropoiesis in children with malaria." (PMID 23521898, 2013). "Constructing a detailed map of polymorphisms around the IL-13 gene and describing a profile of linkage disequilibrium among them will be helpful for further association and functional studies of IL13 polymorphism with severe malaria." (PMID 24312262, 2013). "To conclude, it is known that long-term exposure to malaria causes chronic enlargement of the liver and the spleen and here the levels of three cytokines, IL-12p70, IL-10 and IL-13, and levels of sTNF-RII were found to be associated with both hepatosplenomegaly and exposure to malaria." (PMID 19149774, 2009). "The positive correlation between IFN-γ and anti-inflammatory or eosinophil-related cytokines such as IL-5 and IL-13 suggests that a balance of co-increasing pro-inflammatory and anti-inflammatory cytokines in a suitable range may benefit malaria clearance and prognosis." (PMID 41552719, 2025). "Our data revealed that infected baso IL-4/IL-13 (−) mice exhibited increased ileal mastocytosis, intestinal permeability, and bacteremia relative to infected controls, suggesting that basophil-derived IL-4 and IL-13 blunt MC-dependent intestinal permeability and bacteremia in malaria." (PMID 38780542, 2024). "Befitting any general immune response mechanism, various cytokines may potentially modulate ICAM1 expression, of which we have found evidence for statistical association of IL1, IL4 (and its receptor, IL4R), IL6, IL13, TLR2, TLR4, and IFNG (and its receptor, IFNGR1) polymorphisms with malaria." (PMID 37287037, 2023). "Interestingly, IFN-γ, IL-6 and IL-13 displayed the highest relative number of network interactions in the group of dengue mono-infected patients, whereas IL-12p70 exhibited the highest relative number of interactions in the malaria mono-infection group." (PMID 26271921, 2015). "In a prospective birth cohort study in Kenya, children of malaria-infected women whose CBMC did not produce cytokines (IFN-γ, IL-2, IL-13, and/or IL-5) in response to blood stage malaria antigens were at increased risk of infection and had lower hemoglobin levels during childhood." (PMID 24130857, 2013). "IL-6, IL-13, TNF-α, and IFN-γ were significantly higher in severe malaria, while IL-7, IL-10, IL-17, and IL-27 showed the opposite trend." (PMID 36293524, 2022). "Genomic scans suggest that immunity genes such as AKT3 and IL13 (possibly involved in simian immunodeficiency virus defense), and G6PD, a gene involved in malaria resistance, are under positive natural selection." (PMID 32986826, 2021). "Circulating levels of interferon (IFN)-γ, interleukin (IL)-2, IL-4, IL-6, IL-10, IL-12p70, IL-13, IL-17A and tumor necrosis factor (TNF) were assessed in sera of patients infected with active VL and/or malaria and healthy individuals from Gedarif State, Sudan." (PMID 24886212, 2014).
malaria (continued). "Consequently, the current study investigated the associations between two IL-13 promoter variants, haplotypes and susceptibility to SMA in a phenotypically well-defined cohort of children aged 3–36 months presenting with clinical symptoms of malaria in a rural setting of western Kenya." (PMID 23521898, 2013). "Malaria and dengue coinfections showed a significant increase in proinflammatory cytokines such as IFN-γ, IL-1, IL-6, and IL-12; Th2 cytokines such as IL-4; anti-inflammatory cytokines such as IL-10 and IL-13; and Th17 cytokines such as IL-17." (PMID 36716305, 2023). "Distinct cytokine profiles in malaria and CHIKV coinfections were IFN-γ, IL-4, IL-12, and IL-13." (PMID 36716305, 2023). "Thus, the PBMC of malaria patients were stimulated with iRBC and their production of IFNγ, IL10, TNFα, and IL13 was measured by intracellular staining." (PMID 27802341, 2016). "In addition, AST seemed to be highly influenced by immune molecules in the malaria and dengue co-infected patients as this enzyme was positively correlated with CCL2, IL-13 and IL-8." (PMID 26271921, 2015). "Severe malaria was also associated with higher levels of IL-1β (p = 0.008), IL-2 (p = 0.001), IL-4 (p = 0.041), IL-12p70 (p = 0.010), IL-13 (p = 0.004), IFN-γ (p = 0.041), TNF (p = 0.049), IFN-γ/IL-10 (p = 0.016), TNF/IL-10 (p = 0.016) and (TNF + IFN-γ)/IL-10 (p = 0.001) than mild malaria." (PMID 26466783, 2015). "In the group of patients with malaria and dengue co-infection, HB and HT displayed negative associations with IL-7, whereas AST exhibited positive interactions with CCL2, IL-13 and IL-8." (PMID 26271921, 2015). "Previous studies have demonstrated that increased IL-13 production exacerbate infectious diseases and allergic disorders, alter immune responses in malaria, and is potentially a negative predictor of Hb levels in children with malarial disease." (PMID 23521898, 2013). "Allele frequencies for two SNPs in genes that code for IL-13 and TRIM-5 were found to be significantly different between those who have experienced one or more malaria attacks within past 10 years and those who did not." (PMID 22905743, 2012). "Moderate associations were found between some immune response genes (ie, IL3 and IL13) and parasite rates, but these could not be reproduced using the alternative measures of malaria propensity." (PMID 28541483, 2017). "Furthermore, two SNPs (rs848, rs1881457) in IL-13 gene were found to be significantly different between those who have experienced one or more malaria attacks within past 10 years and those who did not in Sri Lanka." (PMID 23316245, 2012). "However, for the malaria group, four distinct correlation patterns were observed; first pattern (CCL4, CCL2, CCL3, IL12 and IL2), second pattern (IL-17A, IL-1β, CCL11, IL4), third pattern (IL5, IL7, IL13), and fourth pattern (IL1RA, CXCL10, TNFα, IL2R, CXCL9, IL6)." (PMID 35811678, 2022). "Although P. vivax and P. falciparum malaria patients have similar cytokine profiles during infection, in P. vivax acute phase malaria, APRIL but not BAFF levels correlated positively with IL‐1, IL‐2, IL‐4, IL‐6, and IL‐13 levels." (PMID 29314720, 2018). "Indeed, our findings showed that, in P. vivax acute phase malaria, APRIL but not BAFF levels correlated positively with IL‐1, IL‐2, IL‐4, IL‐6, and IL‐13 levels." (PMID 29314720, 2018).
atherosclerosis (39 papers, 2008 to 2025). A disease characterized by the build-up of fatty material and calcium deposition in the arterial wall resulting in partial or complete occlusion of the arterial lumen. "In contrast, Binder and colleagues demonstrated that Il13-deficiency promotes atherosclerosis and that pharmacological treatment with IL-13 induces pro-resolving macrophage polarization in plaques." (PMID 36994095, 2023). "As the major and direct consequence of dyslipidemia, atherosclerosis can be attenuated by Th2-associated cytokines, such as IL-5 and IL-13, according to previous studies." (PMID 35265637, 2022). "As was observed with the ILC2-specific IL-5 deficiency, the inability of ILC2 to produce IL-13 significantly increased atherosclerosis in the aortic arch." (PMID 28589929, 2017). "The reason we chose these specific cytokines in this study isthat they are considered to be effective in inflammation underlying atherosclerosis.Previous studies showed that cytokine IL-13 may prevent progression ofatherosclerosis." (PMID 33711092, 2021). "Although the precise mechanism linking the genetic mutants to plasma levels of IL13 is not yet fully understood, understanding the potential mechanism could provide valuable information on the underlying mechanisms of atherosclerosis and plaque instability, which are key factors contributing to MI." (PMID 39088580, 2024). "In addition, several studies have demonstrated that M1 macrophage phenotype is linked to atherosclerosis progression and, in turn, the induction of macrophage polarization to M2 by IL-13 could reduce disease progression." (PMID 34070749, 2021). "Animal models of IL-13 deficiency suggest IL-13 may act as a contributor in atherosclerosis." (PMID 30759882, 2019). "Dupilumab is a fully human monoclonal antibody that has been shown to reduce and downregulate pro-inflammatory cytokines such as IL-4 and IL-13, which are key mediators in AD and also involved in the pathogenesis of cardiovascular diseases and atherosclerosis." (PMID 40922830, 2025). "Anti-inflammatory cytokines (such as interleukin (IL)-5 and IL-13) mitigate atherosclerosis, whereas pro-inflammatory cytokines (such as IL-1, IL-6) quicken the disease’s course." (PMID 40160593, 2025). "Transfer of IL-13-producing Treg cells into mice with atherosclerosis improved lesional efferocytosis by promoting macrophage efferocytosis during the resolution of inflammation." (PMID 39578419, 2024). "Th2 cells, known for their anti-inflammatory properties, can delay or potentially reverse atherosclerosis progression, primarily via the secretion of cytokines like interleukin 4 (IL-4), interleukin 5 (IL-5), and interleukin 13 (IL-13)." (PMID 39200308, 2024). "Similar results have been described in the presence of IL-13-producing Treg cells in atherosclerosis." (PMID 39578419, 2024). "Administration of IL-13 in atherosclerosis models has been shown to stabilize atherosclerotic plaques via inducing collagen expression 97 and inhibiting monocyte/macrophage infiltration." (PMID 38774746, 2024). "In contrast to IL-4, Th2 -derived IL-5 and IL-13 antagonize the Th1 response and show a protective effect in atherosclerosis." (PMID 38774746, 2024). "In mice that received IL-13−/− bone marrow, atherosclerotic lesions showed an increased necrotic core formation and accelerated atherosclerosis compared to IL-13+/+ mice." (PMID 37681883, 2023). "For example, by promoting the polarization of inflammatory macrophages in atheroma plaques towards an anti-inflammatory phenotype, IL-13 reduces atherosclerosis." (PMID 37475858, 2023). "To confirm that plaque IL-13 levels are negligible, we examined its expression in a recently published dataset of plaque immune cells pre- and post-atherosclerosis resolution." (PMID 33720008, 2021).
atherosclerosis (continued). "The main Th2 cytokine is IL-4, which suggests a disease‐promoting effect, while Th2-secreted IL-5 and IL-13 have a protective effect in atherosclerosis patients." (PMID 34915859, 2021). "A somewhat related activity of IL-13, also possibly involving macrophage activation, is regulation of atherosclerosis, where the precise role and mechanism and its clinical significance remain to be elucidated." (PMID 30759882, 2019). "Other studies suggest that IL-13 leads to atherosclerosis by inducing expression of peroxisome proliferator activated receptor δ (PPARδ) or PPARβ in the adipose tissue and by increasing CD36 levels." (PMID 30759882, 2019). "Taken together, ginsenoside Rb1 protected against atherosclerosis by promoting M2 macrophage polarization and limiting intraplaque inflammatory response, which was achieved by increasing the production of IL‐4 and IL‐13 and STAT6 phosphorylation." (PMID 28944992, 2018). "Interleukin-13 (IL-13) has important functions in atherosclerosis, but its role in coronary artery disease (CAD) is unclear." (PMID 29670225, 2018). "Studies have also reported that IL-13, IL-5 and IL-4 all participate in the pathological process of atherosclerosis, which is the major pathogenesis of CAD12,25–27." (PMID 29670225, 2018). "We designed reconstitution experiments to address the specific roles of ILC2-derived IL-5 or IL-13 in the control of atherosclerosis." (PMID 28589929, 2017). "On the contrary, in the development of atherosclerosis, IL-33 markedly increased the levels of IL-4, IL-5, and IL-13, and decreased the level of IFN-γ." (PMID 28423665, 2017). "These include in particular Th1-cell lineage which are pro-atherogenic via the secretion typically of IFN-γ and TNF-α, and Th2-cell lineage secreting IL-4, IL-10 and IL-13 whom their role in atherosclerosis remains controversial, including Th1 and Th2 cells." (PMID 26600018, 2015). "It was assumed that IL-13 would have a similar pro-atherogenic role in atherosclerosis as IL-4, because both cytokines share similar functions by engaging the same receptor complexes." (PMID 23027612, 2012). "To study the capacity of IL-13 to influence existing atherosclerosis, we performed an intervention study in which IL-13 was administered exogenously to mice with established atherosclerotic lesions." (PMID 23027612, 2012). "Th2 cells secrete IL-4, IL-5 and IL-13, among which IL-5 and IL-13 have been shown to have a protective effect on atherosclerosis, and IL-13 can reduce the infiltration of macrophages in plaques by decreasing the expression of vascular cell adhesion molecule-1 (VCAM-1)." (PMID 41268556, 2025). "Furthermore, Th1 cells are the main type of CD4+ T cells in AS, which produce a large number of pro-inflammatory cytokines, while Th2 cells can produce IL-13 and IL-5 to antagonize atherosclerosis." (PMID 36969166, 2023). "Th2-related cytokine interleukin (IL)-4 may be a critical cytokine in early atherosclerosis progression, but IL-13 demonstrates a protective effect." (PMID 37334359, 2023). "More interesting is the role of IL-13 in the development and progression of atherosclerosis." (PMID 37629267, 2023). "In addition, in a mouse model of atherosclerosis, IL-13 acted anti-atherogenic by inducing M2 polarization." (PMID 35488301, 2022). "Researchers have concluded that in atherosclerosis, interleukins such as IL-4, IL-13, and IL-10 activate specific transcription factors (e.g., STAT3 and STAT6, IFN regulatory factor 3, peroxisome proliferator-activated receptor-γ [PPARγ]) in macrophages to encourage inflammation resolution." (PMID 32346605, 2020). "Decreased IL-13 increased hyperglycemia and hepatic insulin resistance, decreased glucose uptake and then accelerated atherosclerosis, and this might be a slow and cumulative process." (PMID 29670225, 2018).